ABCG2 (ATP binding cassette subfamily G member 2 (JR blood group))
Diseases named in the same sentence as ABCG2 in open-access papers (continued):
Sharing a sentence is not in itself a finding about the gene and the disease.
cancer (continued). "Another study demonstrated the effects of FaOH, FaDOH, FaDOH3Ac and falcarindiol 3,8-diacetate on breast cancer multidrug resistance protein (BCRP/ABCG2), a xenobiotic efflux transporter that causes chemotherapy resistance in cancer." (PMID 36981118, 2023). "From the large number of factors analysed, only a few were found to be connected with ABCG2 expression, and different associations were observed for distinct anatomic cancer locations." (PMID 37445716, 2023). "This rise in the level of ABCG2 protein helps pump out the chemotherapy drugs from the cancer cells thereby causing drug resistance." (PMID 37166017, 2023). "ABCG2 polymorphisms are known to contribute to multidrug resistance in cancer chemotherapy and have a correlation with survival rates and therapy response in cancer." (PMID 37185752, 2023). "ABCG2 was reported to be closely linked with tumour progression and oxaliplatin resistance in many types of cancer." (PMID 37621132, 2023). "In ATC, high expression levels of ABCB1, ABCC1 and ABCG2 observed in several cell lines and tissues, were associated with cancer drug resistance." (PMID 35837087, 2022). "Unexpectedly, we found that ABCG2 expression was negatively associated with cancer stem-like features, RNAss among most types of cancers." (PMID 36555598, 2022). "The most important transporter responsible for the active removal of TOP from cancer cells is BCRP (Breast Cancer Resistant Protein) encoded by the ABCG2 gene." (PMID 35628654, 2022). "ABCG2, which belongs to the same family of transporters, has been implicated in stem-cell protection and associated with some cancers." (PMID 36077209, 2022). "In this study, we sought to determine the potential impact of P-gp and ABCG2 on the susceptibility of human cancer cells to the second-generation ALK inhibitor ensartinib." (PMID 35565470, 2022). "The expression of ABCG2 has been implicated in multiple drug resistance and poor prognosis in several cancer types." (PMID 36158120, 2022). "The relationship between common ABCG2 variants and cancer risk is complex and controversial, and the main differences seem to be dependent on population and cancer type." (PMID 36077209, 2022). "In the present study, we investigated the interaction between ensartinib and two main ABC drug transporters (P-gp and ABCG2) to determine the potential impact of these multidrug efflux transporters on the susceptibility of human cancer cells to ensartinib." (PMID 35565470, 2022). "Approximately 44% and 32% cancerous tissues overexpressed mdr1 and ABCG2 respectively, showing a significant association (P = 0.0113 and P = 0.02) with cancer risk." (PMID 37092084, 2022). "mdr1 and ABCG2 are two important genes of ABC transporter pathway that are thought to be mutated and ultimately leading to cancer initiation." (PMID 37092084, 2022). "ABCG2 is abundant in the side population phenotype in CSCs and effluxes Hoechst 33342 from cancer cells, associating ABCG2 with multidrug resistance." (PMID 35719973, 2022). "The cDNAs of cancer cell lines were collected to detect exon mutation sequences and to analyze ABCG2 mRNA expression." (PMID 36555598, 2022). "To extend the cellular effect of NDG1 to molecular presentations, we determined the expression of cancer stemness-associated regulators (ABCG2, Twist1, BMI1, NES, c-Met) in NDRG1-FL-transfected HNC cells." (PMID 35563887, 2022). "Three paradigm ABC transporter members, ABCB1 (P-gp), ABCC1 (MRP1) and ABCG2 (BCRP) appear to act as brothers in arms in promoting or causing MDR in a variety of therapeutic cancer settings." (PMID 33946618, 2021). "BCRP/ATP-binding cassette subfamily G member 2 (ABCG2) is also an ABC transporter identified as a molecular cause of MDR in diverse cancer cells." (PMID 34589084, 2021).
cancer (continued). "ABCG2 has been widely reported to be a principal cause of MDR in various cancers via pumping out various antineoplastic drugs such as tyrosine kinase inhibitors (TKIs), topoisomerase inhibitors, anthracyclines etc.." (PMID 34572902, 2021). "The genetic variants of ABCG2 were reported to be involved in cancer risk and chemotherapeutic response." (PMID 33509236, 2021). "ABCG2 mutations/polymorphisms in connection with anti-cancer drug-elicited ADRs will be discussed in the following subsection." (PMID 33801813, 2021). "It is worth also noting that the anti-cancer agent mitoxantrone also promote cellular processing of various ABCG2 variants, exemplified by Q141K, the accumulation of which in aggresomes was prevented by mitoxantrone." (PMID 33801813, 2021). "Dysregulated ABCG2 overexpression is linked with poor prognosis in several cancer types, with particularly low survival in AML patients." (PMID 33946618, 2021). "It lowered the expression of CSC markers CD44, ABCG2, Sox2, and Nanog, attenuated cancer stem cell-associated spheroid formation, and inhibited the JNK signaling pathway." (PMID 34884848, 2021). "Previous studies have reported that tyrosine kinase inhibitors (TKIs) such as imatinib and sunitinib are transported substrates of ABCB1 and ABCG2 and the overexpression of ABCB1 or ABCG2 in cancer cells results in reduced susceptibility to TKIs." (PMID 31941029, 2020). "The most intriguing finding was the association of efflux transporters ABCB1 and ABCG2 with favourable OS in cancers." (PMID 33202946, 2020). "ABCG2 has been characterized as a transporter causing of MDR in many human cancers by actively transporting chemotherapeutic agents out of cancer cells." (PMID 33692943, 2020). "Simultaneously, a side population (SP) analysis was performed to detect stem-like cancer cell populations based on their high expression of ABCG2, which is a transporter of Hoechst 33342 and causes its exclusion from cells." (PMID 32194819, 2020). "We found a significant association between ABCG2 basolateral immunoreactivity in the cancer cells and response to irinotecan containing therapy in chemo-naïve patients with mCRC." (PMID 32708825, 2020). "ABCG2 mRNA and protein expression levels were inversely associated with cancer severity and patients’ survival." (PMID 33066132, 2020). "As a major drug transporter of substrates across extra- and intra-cellular membranes, ABCG2 overexpression has been associated with multidrug resistance in various cancer diseases." (PMID 32708825, 2020). "Variations in expression patterns (mainly in ABCB1/multidrug resistance protein (MDR1), ABCG2/BCRP and ABCCs/MRPs) have been linked to toxicity and resistance to therapeutic agents, particularly in cancer chemotherapy." (PMID 33128234, 2020). "The effects of shrimp miR-965 on the expression of cancer stemness-associated genes (ABCG2, ALDH1, Nanog, and Oct-3/4) were detected with qPCR." (PMID 32586376, 2020). "To define the association of ABCG2 expression and cancer stemness in HNC cells, we determined ABCG2 protein expression in a SAS sphere culture system." (PMID 32957726, 2020). "ATP-binding cassette G2 (ABCG2) is a membrane protein-associated drug resistance and stemness in cancers." (PMID 32957726, 2020). "We also examined expression of several signaling molecules whose expression has been associated with chemo-resistance in other cancer types, such as ABCG2, c-FLIP, BCL2." (PMID 30382189, 2019). "It has a broad substrate spectrum and can transport various anticancer drugs, including SN-38, methotrexate, topotecan, and imatinib, which means that overexpression of ABCG2 by cancer cells causes multidrug resistance." (PMID 31340525, 2019). "In line with this notion, the somatic mutation R482G, a mutation that frequently occurs in drug-resistant cancer cells, has been associated with an altered ABCG2 substrate spectrum, e.g., with respect to cytotoxic drugs." (PMID 29867471, 2018).
cancer (continued). "Of these, ABCB1/P-gp, ABCC1/MRP1, and ABCG2/breast cancer resistance protein are primarily associated with MDR." (PMID 29670920, 2018). "Compared to parental cells, ABCG2 overexpression—which was associated with boosted autophagy—rendered cancer cells more rendered cancer cells more resistant to stress inducers." (PMID 29066973, 2017). "Non‐toxic concentrations Saq‐nitric oxide caused sensitization of ABCB1‐, ABCC1‐ or ABCG2‐overexpressing cancer cells to chemotherapy." (PMID 26864945, 2016). "ABCB1, ABCC1 and ABCG2 are the ABC transporters most frequently been associated with MDR in cancers." (PMID 27689338, 2016). "Among these, ABCB1 (p-glycoprotein/MDR1), ABCC1 (MRP1) and ABCG2 (BCRP1) are the major drug transporters which have been widely implicated in drug resistance in several cancers." (PMID 27171227, 2016). "ABCG2 was supposed to contribute to xenobiotica protection for stem cells and underlies the ability of cancer cells to regenerate post-chemotherapy." (PMID 27834829, 2016). "The genetic variants of the ATP-binding cassette, subfamily G, member 2 (ABCG2) are known to be involved in developing cancer risk and interindividual differences in chemotherapeutic response." (PMID 26634205, 2015). "Expression of the TIC marker CD133 in several cancers is shown to be associated with increased expression of drug transporters like ABCG2." (PMID 26597727, 2015). "The results showed that stemness genes (Nanog and Oct-4), multiple drug-resistant transporter gene (ABCG2) and surface antigens associated with cancer stem cells (CD24, CD44 and CD133) were upregulated in ZIPK-transfected cells compared with control cells." (PMID 25831050, 2015). "ABCG2 has also been implicated in another realm of cancer that is somewhat separate from treatment response: the cancer stem cell (CSC) phenotype." (PMID 26714461, 2015). "The breast cancer resistance protein (ABCG2) is another ABC transporter that has been identified as a molecular cause of multidrug resistance in diverse cancer cells." (PMID 25663899, 2015). "Although the associations between ABCG2 gene polymorphisms and carcinoma risk and prognosis have been evaluated for these carcinomas, the genetic effect of the ABCG2 polymorphisms on the susceptibility and prognosis of BC is still unclear." (PMID 26634205, 2015). "To date, only few studies have investigated the association between the ABCG2 polymorphisms and the susceptibility and survival of carcinoma." (PMID 26634205, 2015). "Arthropod ABCG genes are orthologous of the human gene ABCG2, which has been associated with resistance to cancer drugs, while data in insects show that ABCG transporter genes were significantly over-transcribed in response to exposure to insecticides." (PMID 25073980, 2014). "Further identification and characterization of mechanisms directly connecting ABCG2 to CS-associated apoptosis and signaling are mandatory for establishing a new therapeutic strategy, selectively targeting and eliminating resistant cancer cells." (PMID 24312054, 2013). "Plumbagin is also known to act as an inhibitor of multidrug resistance-linked ATP-binding cassette drug transporter ABCG2, a protein responsible for the drug efflux in cancer cells." (PMID 23971004, 2013). "ABCG2 has also been implicated in cancer susceptibility, as a polymorphism in the human gene is associated with a change in incidence for several malignancies." (PMID 24219920, 2013). "The membrane transporter protein ABCG2 is linked to multi-drug chemoresistance in cancer cells due to its ability to reduce the intracellular concentrations of anticancer drugs using the energy of ATP hydrolysis to transport drugs across the cell membrane." (PMID 23599788, 2013). "More studies are needed to explore the relationship between C421A polymorphism in ABCG2 and cancer risk." (PMID 22937733, 2012).
cancer (continued). "ABCG2 is an important efflux transporter of xenobiotic compounds, including many antineoplastic drugs, and its inhibition or mutation can improve cancer chemotherapy." (PMID 23369448, 2012). "The results indicated that the overall significance of the ORs was not altered by any single study in the genetic models for the C421A polymorphism in ABCG2 and cancer susceptibility which suggested the stability and liability of our overall results." (PMID 22937733, 2012). "When stratified by cancer, source of controls and ethnicity classification, the C421A polymorphism of ABCG2 was also an important protective factor against cancer development in the subgroups studied." (PMID 22937733, 2012). "In conclusion, this meta-analysis demonstrates that the ABCG2 C421A polymorphism is associated with a decreased risk of cancer and is likely a protective factor against cancer development." (PMID 22937733, 2012). "To date, numerous studies have investigated the association between the C421A polymorphism in ABCG2 and the cancer susceptibility." (PMID 22937733, 2012). "In recent studies, ABCG2 expression has been also associated with stem cells and cancer stem cells, both in circulating and solid cancers." (PMID 23153066, 2012). "The closest ortholog to this gene in humans is ABCG2, which has been associated with resistance to cancer drugs." (PMID 23049917, 2012). "Genetic polymorphisms and transcriptional activation in the ABCG2 (BRCP) transporter influenced cellular accumulation of porphyrin derivatives in cancer cells leading to individual differences of patients in their response to photodynamic therapy." (PMID 21645349, 2011). "ABCB5 is a member of the ABC protein superfamily, which includes the transporters ABCB1, ABCC1 and ABCG2 responsible for causing drug resistance in cancer patients and also several other transporters that have been linked to human disease." (PMID 21298007, 2011). "Whereas non-SP cells formed fewer and slower-growing tumours, SP cells over-expressed many genes associated with cancer stem cell and drug resistance: ABCG2, FGF1, IGF1, MYC, SOX1/2, WNT1, as well as genes involved in angiogenesis, Notch and Hedgehog pathways." (PMID 20424609, 2010). "One of these members, ABCG2 which is thought to exist and work as homo-oligomers of 8–12 subunits, has also been implicated to play roles in protecting cancer stem cells, resulting in drug resistance and failure of cancer chemotherapy." (PMID 19479068, 2009). "All these previous observations make ABCG2 an ideal target for development of chemo-sensitizing agents for better treatment of drug resistant cancers and suggest that inhibiting ABCG2 unlikely will cause any side effect if the inhibitor is specific to ABCG2." (PMID 19479068, 2009). "It was reported that ABCG2 pumping out the drugs was associated with multi-drug resistance in many cancers and/or effects higher levels of DNA repair and hence lowered the ability to apoptosis." (PMID 18034892, 2007). "Furthermore, GNP-DSH-WFA markedly decreased the expression of ATP-binding cassette subfamily G member 2 (ABCG2), a protein frequently observed in cancer cells and strongly linked to the development of multidrug resistance." (PMID 40448105, 2025). "Notably, the ATP-binding cassette transporter G2 (ABCG2), a key efflux protein implicated in multidrug resistance, is significantly upregulated in 3D spheroids and cancer stem-like cells." (PMID 41323785, 2025). "However, treatment with Carbo, Carbo + Pxt and Carbo + Gem led to increased ABCG2 expression, potentially linked to the cancer's advanced stage and a higher likelihood of developing treatment resistance." (PMID 40572053, 2025).
cancer (continued). "P-glycoprotein/multidrug resistance protein 1 (P-gp/MDR1/ABCB1), multidrug resistance-associated protein 1 (MRP1/ABCC1), and breast cancer resistance protein (BCRP/ABCG2) are the most significant ABC transporters clinically proven to be associated with multidrug resistance during cancer therapy." (PMID 41154409, 2025). "Elevated ABCG2 expression has been implicated in cancer progression and poor clinical outcomes." (PMID 39403600, 2024). "In addition to its role under physiological conditions, ABCG2 has been associated with the chemoresistance of several cancers." (PMID 38612927, 2024). "Notably, there is a strong association between cancer stem cells and the emergence of chemoresistance, and in fact both ABCG2 and ABCB1 are expressed in cancer stem cells." (PMID 38254110, 2024). "Advances in elucidating the molecular basis of the MDR phenotype have indicated that elevated membrane expression of drug efflux pumps such as P-glycoprotein (Pgp or ABCB1), multidrug resistance protein 1 (MRP1 or ABCC1), and ABCG2 is a frequent cause of MDR in human cancers." (PMID 37108495, 2023). "ABCG2 has also been implicated in the cancer stem cell (CSC) phenotype." (PMID 37190293, 2023). "Several factors (i.e., phenotype changes) contribute to the plasticity of cancer cells, such as mutations in the androgen receptor and overexpression of the protein ABCG2, which in turn contributes to the production of chemical castration-resistant cancer cells." (PMID 38131796, 2023). "HCP1 upregulation and ABCG2 downregulation, induced by ROS production, elevated intracellular porphyrin accumulation and elicited an increase in cytotoxicity caused by laser irradiation in X-ray-resistant cancer cells." (PMID 38004516, 2023). "Moreover, ABCB1 or ABCG2 overexpression in cancer cells is often associated with multidrug resistance (MDR) and poor prognosis in patients with solid tumors or hematologic cancers." (PMID 36361555, 2022). "Moreover, investigations of the correlation of ABCG2 gene mutations with ABCG2 transport activities and further clinical pharmacogenetic studies have also been carried out in various types of cancer." (PMID 36555598, 2022). "ABCG2 encode breast cancer resistance protein (BCRP), which is the ATP-binding cassette transporter mediating efflux of xenobiotics including temozolomide and other low molecular weight anti-cancer drugs from the endothelium away from the neuro parenchymal space." (PMID 34222002, 2021). "Furthermore, accumulating evidence reported that PpIX appears to be pumped out of cancer cells by ABCG2, which is associated with multidrug resistance-associated protein." (PMID 33670777, 2021). "Consequently, the overexpression of ABCG2 in cancer cells is linked to the development of the multidrug resistance (MDR) phenotype." (PMID 34502348, 2021). "This phenomenon could be related to the increased expression of ABCB1 and ABCG2 in resistant variants of A2780 cancer cell line." (PMID 31991882, 2020). "Among the ABC proteins, three transporters, P-glycoprotein (P-gp or ABCB1), the multidrug-resistance-associated protein-1 (MRP1 or ABCC1) and the breast cancer resistance protein (BCRP or ABCG2) are mainly associated with cancer MDR being overexpressed in many cell lines." (PMID 32290281, 2020). "Consequently, ABCB1- and ABCG2-overexpressing cancer cells are less susceptible to treatment with these RTKs inhibitors." (PMID 32466597, 2020). "Abcg2 is an efflux pump associated with the drug resistance of cancer stem cells." (PMID 32610610, 2020). "For example, ABCG2 variants are likely to affect the milk yield and composition in Holstein cattle and the development of gout and drug resistance in human cancer cells (e.g., breast, colon and liver cancer cells)." (PMID 32664916, 2020). "Overexpression of ABCB1, ABCC1, and/or ABCG2 is a major cause of MDR in cancer." (PMID 33066132, 2020).